SHMT1 (serine hydroxymethyltransferase 1)
Diseases named in the same sentence as SHMT1 in open-access papers (continued):
Sharing a sentence is not in itself a finding about the gene and the disease.
squamous cell carcinoma (1 paper, 2024). A carcinoma arising from squamous epithelial cells. "In the TCGA datasets of the two main subtypes of NSCLC, adenocarcinoma (LUAD) and squamous cell carcinoma (LUSC), PSAT1, SHMT1, SHMT2, MTHFD1 and MTHFD2 were significantly overexpressed compared to normal lung tissue." (PMID 38515202, 2024).
thymoma (1 paper, 2020). A neoplasm arising from the epithelial cells of the thymus. "It was inspiring to find that the expression of CNOT family (CNOT2 and CNOT9) and SHMT1 was highly correlated with the prognosis of thymoma: Patients with lower expression of these genes at transcription level had poor relapse‐free survival (RFS) probability." (PMID 31967407, 2020). "CNOT2, CNOT9, CD99, PRSS16, PSMB11, and SHMT1 were found with high abundance in thymoma and participated mainly in nucleic acid and amino acid metabolism." (PMID 31967407, 2020). "Compared with conventional subtyping markers (e.g., TdT, PRSS16, and PSMB11), CNOT2/9 and SHMT1 not only exhibited good segregating capabilities for thymoma and TSCC, but also showed great prognosis indicating potentials." (PMID 31967407, 2020). "Based on the same PRM validation sample batch we also examined TSCC/thymoma marker candidates such as CNOT2/9, SHMT1, VCAN, HTRA1, and TIMP1 in parallel with CK19 in the PRM analysis (for raw fragment abundances of all PRM samples)." (PMID 31967407, 2020). "To visualize their spatial localizations, we applied immunofluorescent stainings by confocal microscopy in type B thymoma tissues using fluorescent‐labeled antibodies of CNOT2, SHMT1, CK19 (to index thymomas epithelia), and DAPI (nuclei staining)." (PMID 31967407, 2020). "Further comparison of type B3 and TSCC proteome revealed a number of differential proteins with similar expression patterns: CNOT2/9 and SHMT1 were found with high abundance in type B3 thymoma, while the abundance of HTRA1, TIMP1, and VCAN was higher in TSCC than in type B3 thymoma." (PMID 31967407, 2020).
triple-negative breast carcinoma (1 paper, 2019). An invasive breast carcinoma which is negative for expression of estrogen receptor (ER), progesterone receptor (PR), and human epidermal growth factor receptor 2 (HER2). "Study of triple negative breast cancer showed that positive stromal SHMT1 was correlated with poor clinical features." (PMID 30755243, 2019).
cancer (65 papers, 2010 to 2025). A tumor composed of atypical neoplastic, often pleomorphic cells that invade other tissues. "Low RFC expression causes the poor capacity to retain intracellular folates in cancer cells, thereby resulting in SHMT1-mediated reliance on cytosolic 1C metabolic flux." (PMID 35531073, 2022). "SHMT1, a critical enzyme regulating one-carbon metabolism, was recently found to be a novel cancer-associated protein." (PMID 30755243, 2019). "Seven genes (BORA, DIS3, POLR2C, FAM175A, EME1, RNF139 and SHMT1) are considered potential biomarkers and/or potential targets for radiotherapy and chemotherapy, as well as cancer susceptibility, cancer progression and metastasis-related genes." (PMID 26517092, 2015). "Folate biosynthesis has been linked to cancer both from studies on dietary supplements and by the identification of polymorphisms in genes encoding enzymes in folate biosynthesis like SHMT1, MTHFR and TS." (PMID 22438825, 2012). "Previous studies underline the capacity of SHMT1 C1420T polymorphism being directly related to cancer susceptibility." (PMID 20920350, 2010). "Serine hydroxymethyltransferase 1/2 (SHMT1/2) is a crucial enzyme in the one-carbon metabolism of tumor cells, and the expression levels of these isozymes have been found to be associated with the biological progression of various malignant tumors." (PMID 38594513, 2024). "In recent years, SHMT1 was found to be a novel cancer-associated protein in human cancers." (PMID 30755243, 2019). "SHMT1 C1420T may lead to the abnormal biosynthesis involved in DNA synthesis and methylation, and it may eventually increase cancer susceptibility." (PMID 26666829, 2015). "Third, other causal genes, which are implicated in the pathogenesis of cancer, might mask the effect of SHMT1 C1420T polymorphisms by gene–gene interactions and, consequently, modulate cancer susceptibility." (PMID 26666829, 2015). "Consequently, abnormally functioning SHMT1 can affect cell progression and ultimately cause cancer." (PMID 26666829, 2015). "Its cytosolic isoform SHMT1 has been widely studied and was reported in progression of various cancer types." (PMID 40432803, 2025). "SHMT1 is involved in the occurrence and progression of many cancers, including gastric cancer, thymic epithelial tumors, pancreatic cancer, and hepatocellular carcinoma." (PMID 40442541, 2025). "SHMT1, one of the key enzymes in the synthetic pathway of serine/glycine and monocarbon metabolism, has been proven to be a new driver gene in human cancer." (PMID 40442541, 2025). "In cancer, SHMT1 sometimes acts as a tumor suppressor, modulating redox homeostasis and inhibiting metastasis, whereas SHMT2 often supports tumor proliferation and survival by enhancing nucleotide biosynthesis and metabolic flexibility." (PMID 40738465, 2025). "Many studies have reported that SHMT1 overexpression can lead to cell growth and the development of malignant tumors." (PMID 40442541, 2025). "Across various cancer types, SHMT1 and SHMT2 exhibit distinct expression patterns and isoform-specific functional roles." (PMID 40738465, 2025). "For example, folate deprived cancer cells increase their reliance on cytosolic SHMT1, while serine/glycine depletioninduces prdominance of the mitochondrial one-carbon pathway." (PMID 37949226, 2023). "Knockdown of SHMT2 in colorectal cancer xenografts completely blocked cancer development only when SHMT1 was also downregulated." (PMID 37664062, 2023). "Cancer cells require SHMT1/2 for optimal tumorigenicity and proliferation, illustrating the importance of serine metabolism in cancers." (PMID 37664062, 2023). "This is in sharp contrast to what is observed by MTHFD2 CRISPR‐Cas9 KO, where cancer cells survive by activating the serine hydroxymethyltransferase 1 (SHMT1) pathway." (PMID 35583750, 2022).
cancer (continued). "Inversely, the transfection of UTR2 in cancer cells can also modulate SHMT1 activity and reduce cell viability, suggesting that it is of great necessity for us to give more studies on the relationship between SHMT1 and SHMT2." (PMID 35531073, 2022). "In proliferating cancer cells, cytosolic 1C pathway flux through SHMT1 is essential to compensate for DNA replication and maintain tumor growth under nutrient-poor conditions." (PMID 35531073, 2022). "The protective effect of SHMT1/2 overexpression includes cancer cell survival through redox maintenance and hypoxic stress reduction." (PMID 36615660, 2022). "In this study, the 1C metabolic flux of cancer cells is switched primarily toward the cytosolic folate cycle through SHMT1 to face nutrient availability under normal physiological folate concentration." (PMID 35531073, 2022). "Intriguingly, the SHMT1/2 inhibitor SHIN1 has been found to notably augment cancer cell proliferation in the presence of the mCI inhibitors metformin, phenformin, and rotenone." (PMID 34439169, 2021). "The miRtron miR-6778–5p, derived from intron 5 of SHMT1 (coding cytoplasmic serine hydroxymethyltransferase), is a pivotal regulator of cancer stem cell stemness in Drosha-silenced gastric cancer cells." (PMID 33330058, 2020). "In LUAD cancer cell lines, SHMT1 plays a major role in controlling cytosolic serine levels, which, in turn, affect cell migration, a property that is required to form metastasis." (PMID 33243973, 2020). "It promotes SHMT1 expression that sustains cancer energy intake via folate-dependent serine/glycine inter-conversion in the one-carbon mitochondrial metabolic pathway." (PMID 33330058, 2020). "Here, we characterize the RNA-binding function of cytosolic SHMT (SHMT1) in vitro and using cancer cell models." (PMID 30809670, 2019). "Collectively, these results demonstrate that WT1 is necessary for transcriptional upregulation of SHMT1, which mediates cancer-promoting activity of WT1." (PMID 28288142, 2017). "The expression of PHGDH (p < 0.001), PSAT1 (p = 0.001), PSPH (p = 0.008), tumoral SHMT1 (p < 0.001), and stromal SHMT1 (p < 0.001) was different according to cancer subtype." (PMID 27277113, 2016). "PSPH and SHMT1 expression in the tumor stroma of HER-2-type cancers was the highest, but the luminal-A tissues showed the lowest expression (p<0.001)." (PMID 24979213, 2014). "Our study and previous studies both showed that SHMT1 can promote the progression of cancer." (PMID 40442541, 2025). "SHMT1 displays variable expression and diverse functional roles depending on cancer type." (PMID 40738465, 2025). "Recent reports indicate that sertraline, a widely used antidepressant in psychiatry, reduces SHMT1/2 activity and could potentially serve as an agent targeting cancers dependent on Ser/Gly synthesis." (PMID 40723225, 2025). "This indicates that SHMT1 cannot be considered as a potential cancer driver in BLCA." (PMID 38594513, 2024). "These actions may stem from the influence of vitamin D on the expression of genes associated with collagen production, such as SHMT1, UGT1A6, and ITIH2.The anti-cancer properties of vitamin D are also supported by changes in KLHL3 and TTPA gene expression." (PMID 38203636, 2023). "Interestingly, although SHMT2 was observed as an oncogenic protein in various cancers, a study showed that SHMT1 inhibited the lung metastasis of HCC cells by suppressing the production of ROS." (PMID 36998464, 2023). "Recently, major variability in cancer cell reliance on cytosolic (SHMT1) versus mitochondrial (SHMT2) serine-derived one-carbon metabolic flux was shown across tumors, suggesting the reduced folate carrier (RFC) as a marker for tumor sensitivity for drug targeting of the cytosolic pathway." (PMID 37980339, 2023).
cancer (continued). "Considering that CX-4945 is a potential anti-cancer therapeutic agent, in view of our data showing the inhibition of CK2 activity causes the increase of DHFR and SHMT1 protein levels, a possible increased survival of cancer cells should be taken into consideration." (PMID 35281258, 2022). "Therefore, cytoplasmic serine starvation induced by SHMT1 knockdown limits the migratory ability of the cancer cells also in the presence of a chemoattractant." (PMID 33243973, 2020). "Since ROS production is closely associated with cellular NADH/NADPH level and is found to regulate the metastasis of cancer cells, we explored whether SHMT1 affected cellular ROS production." (PMID 30755243, 2019). "Our results show that the RNA-mediated inhibition is also effective in cancer cell lines, suggesting that it may contribute to control serine consumption by the cytosolic SHMT1." (PMID 30809670, 2019). "Previous studies showed that SHMT1 is a critical enzyme mediating the one-carbon metabolism, which is implicated in nucleotide synthesis, DNA methylation and NADH/NADPH production in cancer cells." (PMID 30755243, 2019). "Transfection of UTR2 in cancer cells controls SHMT1 activity and reduces cell viability." (PMID 30809670, 2019). "While the mitochondrial isoform of SHMT (SHMT2) has recently been identified as an important player in the control of cell proliferation in several cancer types and as a hot target for anticancer therapies, the role of the cytoplasmic isoform (SHMT1) in cancerogenesis is currently less defined." (PMID 25412303, 2014). "In addition, the function of SHMT1 in cancer is also regulated by miRNA." (PMID 40442541, 2025). "However, the specific role of SHMT1 in metastasis seems to depend on the type of cancer." (PMID 36998464, 2023). "Moreover, small compounds inhibiting SHMT1/2 have been identified for cancer treatment." (PMID 37664062, 2023). "Besides, antifolate compounds are used clinically for treating cancers by inhibiting SHMT1." (PMID 35531073, 2022). "Thus, one can speculate that the SHMT1 repression by DNA methylation depletes the AdoMet synthesis and eventually maintains a lower DNA methylation, a universal finding in cancer." (PMID 25945129, 2015). "Studies of the other two genes we screened, SHMT1 (Serine hydroxy methyl transferase 1) and IFNAR (IFN-α receptor), have focused more on cancer, and studies on fasting or DMI/RFI need to be explored further." (PMID 40184169, 2025). "Serine hydroxymethyltransferases (SHMTs) are key proteins that regulate carbon (methyl) metabolism, including the cytoplasmic isoenzyme (SHMT1) and the mitochondrial isoenzyme (SHMT2), and play a role in metabolic reprogramming in cancers." (PMID 40442541, 2025). "SHMT1 and SHMT2, which are key enzymes in OCM, play distinct yet interconnected roles in cancer progression and metabolic disorders." (PMID 40738465, 2025). "Given their distinct metabolic functions, targeting SHMT1 and SHMT2 is a promising therapeutic strategy for cancer and metabolic diseases." (PMID 40738465, 2025). "SHMT has two distinct isoforms, cytosolic SHMT1 and mitochondrial SHMT2, and a lot of studies pointed out that SHMT2 is a highly relevant cancer drug target." (PMID 39189649, 2024). "SHMT1 and SHMT2 are the key enzymes in 1C metabolism and have been studied as cancer therapeutic targets." (PMID 38279895, 2024). "Targeting both SHMT1 and SHMT2 is essential for SHIN1/2, AGF347 and other compounds to exert potent anti-cancer effects." (PMID 37664062, 2023). "Compared with SHMT1, SHMT2 also exists in various cancers via the conversion of serine and glycine in mitochondria to support cancer cell proliferation." (PMID 37009511, 2023). "It has been demonstrated that SHMT1 can utilize its RNA-binding function to bind the 5′untranslated region of the SHMT2 transcript (UTR2) and control the function of SHMT2-expressed cancer cells." (PMID 35531073, 2022).
cancer (continued). "Although Ser can be synthesized by both SHMT1 and SHMT2, the mitochondrial isoform is strongly upregulated in cancers and has been shown to have a stronger impact on cancer metabolism." (PMID 36428783, 2022). "Among 28 human cancers, 11 cases showed elevated TUFT1 levels, while 17 cases showed decreased SHMT1 levels, compared with the corresponding normal tissues." (PMID 30755243, 2019). "The suppressive role of SHMT1 in HCC metastasis, which was in contrary with the functions of SHMT1 in other tumors, demonstrated the cancer-type dependent function of SHMT1 in different cancers." (PMID 30755243, 2019). "SHMT1/2 and GLDC are important genes in the serine–glycine metabolic pathway that are reported to be upregulated in many cancers." (PMID 29911072, 2018). "Genotyping for BHMT 716A>G, DHFR 19bp ins/del, MTHFD1 1958G>A, MTHFR 677C>T, MTR 2756A>G, MTRR 66A>G, RFC1 80G>A, SHMT1 1420C>T, TCII 776C>G and TS 2rpt-3rpt was performed in 102 cancer patients and 363 cancer-free subjects." (PMID 28968444, 2017). "The serine synthesis pathway is catalysed by several enzymes, such as PHGDH, SHMT1/2, and MTHFD1/2, and their suppression may decrease cancer cell growth and survival." (PMID 37664062, 2023). "In cancer cells SHMT2-mediated mitochondrial one-carbon metabolism is sufficient to maintain the proliferation of most cells, and SHMT1 is usually mediating the reverse reaction that converts glycine to serine by utilizing a one-carbon unit donated by 5,10-methylene THF." (PMID 37949226, 2023). "Mitochondrial 1C flux is consistently overexpressed in cancer and supplied by the folic acid cycle and the mitochondrial serine-hydroxymethyltransferase (SHMT2), while cytosolic 1C flux is induced by the cytosolic enzyme SHMT1." (PMID 35531073, 2022). "The mitochondrial SHMT2, but not cytosolic SHMT1, is highly expressed in cancer cells and tissues and promotes cancer tumorigenesis." (PMID 30804330, 2019). "While SHMT1 is expressed to different degrees across carcinomas, there is not yet any report concerning the role of SHMT2 in human HCC." (PMID 27391339, 2016). "However, a previous study has demonstrated that cancer cells with low expression of SLC19A1 (solute carrier family 19 member 1) rely on SHMT1 rather than SHMT2 for 1C unit synthesis." (PMID 39286657, 2024). "SHMTs comprised two isozymes of SHMT2 and SHMT1 in cells, we performed bioinformatics analysis based on The Cancer Genome Atlas (TCGA) database and found that SHMT2, but not SHMT1, was overexpressed in cancer specimens, with an average 1.522-fold increase compared with controls." (PMID 36806313, 2023). "Therapies that target the single-carbon metabolic pathway, such as serine hydroxymethyltransferases (SHMT1 and SHMT2) inhibition, the key enzymes that convert serine to glycine, and lowering entry of monocarbons to the tetrahydrofolate (THF) cycle, are promising for anti-cancer therapies." (PMID 36578477, 2022). "Moreover, it is exactly that SHMT2 in mitochondria, not SHMT1 in the cytoplasm, was expressed highly in rapidly proliferating cancer cells." (PMID 33163414, 2020). "In addition, binding of the 5′ untranslated region (UTR) of the SHMT2 transcript to SHMT1 protein has been shown to inhibit the enzymatic activity of SHMT134, suggesting an important link between the mitochondrial and cytosolic one-carbon pathway in cancer progression." (PMID 38331894, 2024). "Irrespective of cancer status, several SNPs were found to be associated with altered serum folate concentrations, including the D919G SNP in methionine synthase (MTR), the L474F SNP in serine hydroxymethyl transferase 1 (SHMT1) and the V175M SNP in phosphatidyl ethanolamine methyltransferase (PEMT)." (PMID 29474406, 2018). "Something that has been of interest in cancer studies is that SHMT2, but not SHMT1, has been highly expressed in a variety of cancers, and the inhibition of SHMT2 has also been shown to suppress tumor growth and malignancy." (PMID 39189649, 2024).
cancer (continued). "CRISPR/Cas9-based disruption of SHMT2, but not of SHMT1, prevented metformin from inhibiting total SHMT activity in cancer cell lines." (PMID 34439169, 2021). "Intriguingly, the expression of SHMT1, MTHFD1, and ALDH1L1 had no influence on the survival rate of patients with CRC and LA, suggesting it is not the folate metabolism per se but the THF cycle in the mitochondria that confers poor prognosis in cancers." (PMID 29321536, 2018). "Thus, inhibiting the activity of SHMT1 or SHMT2 alone is not guaranteed to block cell metabolism, and cancer cells might be compensated by using the other." (PMID 38279895, 2024). "One potential explanation for the effective killing with MTHFD2 RNAi but not with CRISPR‐Cas9 could be that cancer cells acutely rely on MTHFD2 to generate thymidine, but easily switch to use the SHMT1 pathway, allowing the clones to survive long term as in the case of CRISPR‐Cas9 KO cells." (PMID 35583750, 2022).